DARS1-AS1 (DARS1 antisense RNA 1)
Synonyms: DARS-AS1
Gene: Long non-coding RNA gene on chromosome 2 (135,985,122 to 136,078,527, forward strand). Ensembl gene ENSG00000231890.
Diseases named in the same sentence as DARS1-AS1 in open-access papers:
DARS1-AS1 is named in the same sentence as 27 diseases in open-access papers, as found by Europe PMC text mining. Sharing a sentence is not in itself a finding about the gene and the disease. The quoted sentences say what the papers report.
ovarian carcinoma (7 papers, 2020 to 2024). A malignant neoplasm originating from the surface ovarian epithelium. "Similarly, as a lncRNA, DARS1 antisense RNA 1 (DARS-AS1)’s carcinogenesis has been testified in ovarian cancer, clear cell renal cell carcinoma, non-small cell lung cancer, and cervical cancer." (PMID 34596006, 2021).
DARS1-AS1 also shares sentences with these, for which no sentence is quoted: tumor (9 papers); multiple myeloma (6); cancer (5); cervical cancer (5); breast carcinoma (3); clear cell renal cell carcinoma (3); hepatocellular carcinoma (3); thyroid cancer (3); glioblastoma (2); lung carcinoma (2); breast tumor (1); chronic kidney disease (1); colon adenocarcinoma (1); colorectal cancer (1); endometrial cancer (1); gastric cancer (1); liver cancer (1); lung adenocarcinoma (1); mesothelioma (1); non-small cell lung carcinoma (1); osteosarcoma (1); prostate carcinoma (1); thyroid (1); triple-negative breast carcinoma (1); uveal melanoma (1); Vestibular schwannoma (1).